EPOR (erythropoietin receptor)
Diseases named in the same sentence as EPOR in open-access papers (continued):
Sharing a sentence is not in itself a finding about the gene and the disease.
Obesity (continued). "Furthermore, the EPO analog ARA290 that activates EPOR in non-erythroid tissue without stimulating erythropoiesis has been shown to positively impact diet-induced obesity and glucose tolerance in mice." (PMID 39996752, 2025). "In addition, the level of EpoR expression in white adipose tissue (WAT), which is secondary to its primary expression site of EpoR in erythroid progenitor cells, suggested the possibility that endogenous EPO action in WAT protects against obesity to maintain energy homeostasis." (PMID 24918289, 2014).
Stroke (13 papers, 2009 to 2026). Sudden impairment of blood flow to a part of the brain due to occlusion or rupture of an artery to the brain. "Expression level of the EPO receptor (EPOR) before the stroke onset has also been associated with improved stroke outcome." (PMID 35151685, 2022). "EPO and EPOR also induce neurogenesis after stroke, early during embryonic development and in vitro via Jak2/Stat3 and PI3K/AKT pathway activation." (PMID 21777449, 2011). "Brain specific ablation of EPOR leads to deficits in neural cell proliferation and neuronal survival in the embryonic brain and in post-stroke neurogenesis in the adult brain." (PMID 20142991, 2009). "In a severe, prolonged stroke, this rapidly-induced cellular defense response (analogous to the parallel up-regulation in neurons of the pro-survival Erythropoietin receptor), will, of course, be overwhelmed by the weight of pro-death signaling (as well as the depletion of cellular ATP)." (PMID 19194497, 2009). "Since both the EPO/EpoR and the JAK2/STAT3 pathways have been implicated as molecular targets for ischemic stroke prevention and treatment, the activation of both of these cell pathways and their downstream signaling cascades is recognized as a promising therapeutic approach for stroke patients." (PMID 28848617, 2017). "Brain-specific genetic ablation of the classical EPOR impairs post-stroke neurogenesis and neuronal survival whereas transgenic brain specific overexpression of human EPO is associated with reductions in postischemic infarct volume, brain swelling and functional deficits in a transient stroke model." (PMID 20142991, 2009). "Mice with EPOR expression restricted to hematopoietic and endothelial tissue and mice with targeted deletion of EPOR in neural cells show no gross morphological defects but do exhibit reduced neural cell proliferation and viability, and increased susceptibility to glutamate damage and stroke." (PMID 32038269, 2019). "Compared with stroke-vehicle control mice, the levels of pro-angiogenic factors VEGF, EPOR, Tie-1 and the neurotrophin BDNF significantly increased in PTH treated mice (n = 3 in stroke and stroke plus PTH groups, respectively; P<0.05)." (PMID 24503654, 2014). "These mice as well as mice with brain specific deletion of EpoR survive through adulthood with no gross morphological defects, although in adult brain, neural cell proliferation and viability were reduced with increased susceptibility to glutamate damage and stroke damage." (PMID 24918289, 2014). "Six days after stroke and PTH or saline treatment, expression of regenerative factors VEGF, EPO receptor (EPOR), Ang-1, Tie-1, Flk-1, BDNF and SDF-1 in the ischemic peri-infarct region were analyzed using Western blotting." (PMID 24503654, 2014). "Mice that retain EPOR expression in hematopoietic tissue but lack EPOR expression in neural cells exhibit no gross morphological defects but show reduced neural cell proliferation and viability, sensitivity to glutamate damage and post-stroke neurogenesis." (PMID 34603036, 2021). "EpoR is also rapidly upregulated in experimental stroke and global ischemia and focal TBI, although upregulation of endogenous Epo/EpoR per se is not sufficient for neuroprotection." (PMID 24344874, 2013). "There is one descriptive study which provides evidence that EPO and EPOR are upregulated in human hypoxic brains lacking quantitative validation, and one study in humans demonstrating serum EPO levels positively correlate with stroke severity and EPO increase with improved functional outcome." (PMID 41602576, 2026). "However, neural-specific EPOR knockdown does not increase infarct volume following focal cerebral ischemia and therefore endogenous levels of EPO may not provide neuroprotection following stroke." (PMID 20339541, 2010).
diabetes (10 papers, 2009 to 2025). "Anti-Erythropoietin Receptor (anti-EPOr) Antibodies: These autoantibodies block the response to EPO in diabetes-associated kidney disease, anti-EPOr antibody levels correlate well with the risk of progression, even in patients without albuminuria." (PMID 40134917, 2025). "The expression of EPOR was also significantly increased 2 weeks after diabetes onset, and it reached a plateau after 1 month." (PMID 30401898, 2019). "When compared with that in the normal control group, the protein expression of EPO and EPOR in the retina in the diabetic group was up-regulated with the progression of diabetes." (PMID 30401898, 2019). "Changes in EPO and EPOR appeared 2 weeks after diabetes onset." (PMID 30401898, 2019). "In rodents, EPO protects against streptozotocin (STZ) induced type 1 diabetes by reversing STZ-mediated β-cell destruction, an activity that is abrogated with EpoR knockout in pancreatic islet, and is protective against diabetes in the db/db mouse model of type 2 diabetes." (PMID 24918289, 2014). "This study was performed to identify EPOR mRNA expression in the human diabetic eye." (PMID 19930719, 2009). "Of note, in addition to deletion of EpoR in fat cells in C57BL/6 mice, a strain commonly used as a model of high fat diet induced diabetes, EpoR was also deleted in fat cells in mice on a mixed background." (PMID 24918289, 2014). "The expression of factors such as HIF-1alpha, VEGF, EPO, EPOR, GFAP and vimentin, was up-regulated with the progression of diabetes in the diabetic rat retinas compared to the expression in normal control retinas, whereas the expression of GS and GLAST was down-regulated." (PMID 30401898, 2019). "In a study of post-mortem retinas of 9 patients with diabetes but without diabetic retinopathy, EPOR was detected in the neuroretina and in the retinal pigment epithelium." (PMID 19930719, 2009). "Unlike its ligand, EPO receptor (EPOR) expression did not change with diabetes (p>0.15)." (PMID 23878504, 2013).
Insulin resistance (10 papers, 2014 to 2025). Increased resistance towards insulin, that is, diminished effectiveness of insulin in reducing blood glucose levels. "Obese EPOR-deficient mice with erythroid-specific EPOR expression exhibited impaired glucose tolerance and insulin resistance, despite having body weight and fat mass comparable to wild-type controls." (PMID 40697664, 2025). "Our results revealed that EPO/EPOR upregulates PPARγ expression to alleviate insulin resistance in hepatocytes." (PMID 26643367, 2015). "In summary, these findings suggest that PPARγ is involved in EPO/EPOR-induced AKT activation, and targeting the PPARγ/AKT pathway via EPO may have therapeutic implications for hepatic insulin resistance and type 2 diabetes." (PMID 26643367, 2015). "Lack of EpoR in nonhematopoietic tissues did in no way impair the efficacy of hypoxia and rhEPO to ameliorate hyperglycemia, glucose intolerance, and insulin resistance, clearly implicating that direct EPO action on nonhematopoietic tissues was not required for glucose lowering." (PMID 40238885, 2025).
lung carcinoma (9 papers, 2013 to 2023). "Interestingly, the loss of EPOR in A549 lung cancer cells reduced the proliferation of tumor xenografts, which has been also observed e.g., in glioma cells, implying that EPOR per se has a regulatory role in cancer cells." (PMID 36052260, 2022). "The expression of EPOR in tumors of lung cancer patients is associated with poor survival." (PMID 36052260, 2022). "Furthermore, we observed that the expression of EPOR is associated with the expression of the mitochondrial marker VDAC1 in tissue arrays of lung cancer patients, suggesting that EPOR indeed helps to regulate mitochondrial biogenesis in tumors of cancer patients." (PMID 36052260, 2022). "Cell type-specific differences in EPOR signalling between primary erythroid and H838 lung cancer cells have recently been defined using a systems biology approach." (PMID 28418910, 2017). "The amount of EPOR protein present in the human lung cancer cell line H838 and its derivative H838-HA-hEPOR was determined by immunoprecipitation followed by quantitative immunoblotting and compared to the amount present in mouse CFU-E cells." (PMID 27494133, 2016). "Lung cancer cell lines found to have the higher levels of EpoR were included in a western with NCI-H838." (PMID 23861852, 2013). "EPO expression score was significantly elevated in lung cancer and lymphoma (compared to benign tissues), while EPOR expression score was significantly elevated in lymphoma, thyroid, uterine, lung and prostate cancers (compared to benign tissues)." (PMID 24004818, 2013). "Although VDAC1 is also differentially expressed by apoptotic regulation, we propose that the approximately 27% (r2 squared Pearson) of VDAC1 variation among the lung cancer biopsies, which was explained by EPOR expression, reflects differences in mitochondrial content." (PMID 36052260, 2022). "In lung cancer patients, coexpression of EPO and EPOR is associated with poor survival." (PMID 36052260, 2022). "Because our data provide convincing evidence that EPOR supports mitochondrial biogenesis in patients with lung cancer, it may be a target to control mitochondrial content and cancer metabolism." (PMID 36052260, 2022). "To validate whether EPOR contributes to the regulation of mitochondrial biogenesis in human lung cancer patients, we analyzed EPOR, iNOS, and VDAC1 expression in lung adenocarcinoma tissue from 19 human patients using immunohistochemistry." (PMID 36052260, 2022). "We observed that both VDAC1 (Pearson’s r = 0.556, p<0.041) as well as iNOS (Pearson’s r = 0.64, p<0.016) correlated with EPOR expression and concluded that EPOR-expressing lung cancer cells showed an increased expression of iNOS and the mitochondrial marker, VDAC1." (PMID 36052260, 2022). "EpoR trafficking dynamics in adherent H838 lung cancer cells closely resembled the dynamics previously characterized by mathematical modeling in suspension cells, indicating that dynamic properties of the EpoR system are widely conserved." (PMID 28945754, 2017). "Therefore, we used human A549 lung cancer cells, which express EPOR." (PMID 36052260, 2022). "In a xenograft model mimicking EPO treatment in lung cancer patients, knockdown of EPOR impaired tumor growth, cellular respiration, mitochondrial content, and iNOS expression and AKT phosphorylation of lung cancer xenografts." (PMID 37746281, 2023). "We then validated these findings by analyzing EPOR and VDAC1 expression in arrays of non-small lung cancer tissue from 214 human patients." (PMID 36052260, 2022). "Furthermore, EPOR and VDAC1, as a surrogate of mitochondrial content correlated positively in most lung cancer types, except for large cell carcinoma." (PMID 36052260, 2022). "Analogous conclusions could also be obtained in lung cancer, prostate cancer and ovarian cancer, which indicated EPO/EPOR signaling system was tightly connected with tumor cell apoptosis, hypoxia resistance and metastasis." (PMID 23825635, 2013).
lung carcinoma (continued). "Finally, EPOR expression and the expression of the mitochondrial marker VDAC1 are positively correlated in biopsies of human non-small lung cancer patients, suggesting that the herein-reported mechanisms exist in tumors of human (lung) cancer patients." (PMID 36052260, 2022). "The absence of either iNOS or pAKT is sufficient to inhibit the EPOR-specific regulation of mitochondrial biogenesis, indicating that AKT and iNOS collectively regulate mitochondrial biogenesis downstream of EPOR in lung cancer cells." (PMID 36052260, 2022).
breast tumor (8 papers, 2008 to 2021). "Thus, our experiments in vitro and in vivo demonstrate that functional EPOR signaling is essential for the tumor-promoting effects of EPO and underline the importance of the EPO-EPOR axis in breast tumor progression." (PMID 28418910, 2017). "While functional EPOR signaling was essential for the breast tumor progression effect of EPO and emphasizes the importance of the EPO/EPOR axis, tumor growth was markedly reduced after the knockdown of EPOR." (PMID 34299300, 2021). "To investigate the role of EPOR in breast tumor progression we used a murine xenotransplantation model which simulated EPO therapy in cancer patients." (PMID 28418910, 2017). "Numerous tumor cells express the EPO receptor (EPOR), posing a risk that EPO treatment would enhance tumor growth, but the mechanisms involved in breast tumor progression are poorly understood." (PMID 28418910, 2017). "EpoR mRNA was largely undetectable in the breast tumor tissues analyzed but readily detectable in the control UT7/Epo cell-line and in human bone marrow cells." (PMID 25807104, 2015). "We also report that there was only no/low level (<100-fold lower than erythroid cells) expression of EpoR protein in a panel of breast tumor cell lines." (PMID 23861852, 2013). "According to IHC and western data, breast tumor sections and the breast tumor cell line MCF-7 were reported to express high levels of EpoR protein." (PMID 23861852, 2013). "Here we extend those studies and show that according to westerns using A82, EpoR protein is undetectable in matched normal and cancerous tissues and was low/undetectable in a panel of breast tumor cell lines." (PMID 23861852, 2013). "Two recent clinical studies implicate EPOR in breast tumor growth." (PMID 28418910, 2017). "Tumor growth in the MDA-MB-231-D3H2-shEPOR subgroup treated with doxycycline (shSCR+dox) was dramatically reduced and showed substantially lower expression of EPOR by in situ hybridization than the control subgroups, indicating that EPO-EPOR axis is active in breast tumor progression in this model." (PMID 28418910, 2017). "Taken together these reports suggest that EPOR expression affects breast tumor progression." (PMID 28418910, 2017). "No EpoR protein was detectable using this method in any of the breast tumor tissues analyzed." (PMID 25807104, 2015).
cervical carcinoma (8 papers, 2008 to 2023). A carcinoma arising from either the exocervical squamous epithelium or the endocervical glandular epithelium. "EPOR is expressed in cervical cancer, and the binding of erythropoietin (Epo) to its receptor induced cell proliferation; such cell response was related to the activation of JAK2, JAK3, STAT3, and STAT5, but not JAK1 and STAT1 in cervical cancer." (PMID 37372319, 2023). "It has been shown that EPO and SCF may have a synergistic effect on erythropoiesis and migration of cervical cancer cells, and EPOR and KIT may even form a receptor complex." (PMID 35887076, 2022).
myelodysplastic syndrome (8 papers, 2014 to 2025). A clonal hematopoietic disorder characterized by dysplasia and ineffective hematopoiesis in one or more of the hematopoietic cell lines. "We report a case of a 65-year-old Japanese woman with low-risk myelodysplastic syndrome (MDS) on hemodialysis who achieved transfusion independence for over eight years with combined epoetin beta pegol (continuous erythropoietin receptor activator, CERA) and roxadustat." (PMID 40666067, 2025). "Although darbepoetin α is the first-choice supportive therapy for low-risk myelodysplastic syndrome, continuous erythropoietin receptor activator might be considered the second-choice therapy." (PMID 29047386, 2017). "In a newly published paper, lenalidomide was shown to increase EPOR levels by inhibiting the E3 ubiquitin ligase RNF41 in cells from the myeloid lineage involved in myelodysplastic syndrome." (PMID 27581518, 2016).
ovarian carcinoma (8 papers, 2012 to 2021). A malignant neoplasm originating from the surface ovarian epithelium. "In contrast, EpoR activation in the same ovarian carcinoma cells leads to Jak activation and elevation of STAT5." (PMID 29393890, 2018). "Accordingly, EpoR has also been reported to be expressed by several types of malignant cells, including ovarian cancer cell lines." (PMID 24982693, 2014). "We report here that murine and human VSELs as well as murine and human teratocarcinoma cell lines and ovarian cancer cell lines share a functional EpoR." (PMID 24982693, 2014). "Similar findings were found in ovarian carcinoma A2780 cell with down-regulated EpoR, in which p-AKT increased for compensatory mechanisms." (PMID 23028796, 2012). "Studies on ovarian carcinoma cells, that endogenously express both EphB4 and EpoR, demonstrated that both ephrin-B2 and Epo directly activate EphB4, causing increased proliferation and invasive migration mediated by Scr kinase (a cytosolic non-receptor tyrosine kinase) and STAT3." (PMID 29393890, 2018). "Similarly, injection of an anti-Epo antibody or the soluble form of EpoR into xenograft mice of uterine and ovarian cancer models reduced capillaries leading to tumor destruction." (PMID 26919105, 2016). "To address a potential link between VSELs and germ line cells we analyzed by RT-PCR and FACS expression of erythropoietin receptor (EpoR) on murine bone marrow- and human umbilical cord blood-derived VSELs, murine and human teratocarcinoma cell lines and human ovarian cancer cells." (PMID 24982693, 2014). "Based on evidence that several cancer cell lines, including ovarian cancer cells, express EpoR, we became interested in whether functional EpoR is expressed by murine and human germline-derived cell lines." (PMID 24982693, 2014). "In addition, after the downregulation of EPOR, both phosphorylated EPOR and STAT5 levels significantly decreased and either pAKT in ovarian carcinoma cells or pERK1/2 in human renal carcinoma cells were increased as a compensatory mechanism." (PMID 34299300, 2021). "Moreover, survival of patients with breast and ovarian cancers was reduced with increased expression level of EphB4 but not of EpoR, and Epo treatment further reduced the survival chances of breast cancer patients with tumors that express high levels of EphB4." (PMID 29393890, 2018). "Similarly, increased baseline phosphorylation of EpoR signaling proteins and no biological effects of exogenous Epo were also found in A2780 human ovarian carcinoma cell line." (PMID 23028796, 2012). "EPOR and its downstream signaling pathways STAT5, PI3K/AKT, and MAPK were found as constitutively active and independent of EPO stimulation in non-small cell lung, renal, and ovarian cancer cells but the mechanism underlying this phenomenon is not sufficiently described." (PMID 34299300, 2021).